TNF (tumor necrosis factor)
Diseases named in the same sentence as TNF in open-access papers (continued):
Sharing a sentence is not in itself a finding about the gene and the disease.
tumor (continued). "One day after perfusion with actinomycin D in combination with TNF the rats limb was severely swollen with oedema and the remaining tumour was barely visible." (PMID 11953868, 2002). "Other molecules which can induce apoptosis especially in tumour cells are TNF-α and TNF-related apoptosis inducing ligand (TRAIL)." (PMID 11875749, 2002). "Initially thought to have anti-tumour effects, TNF-α was later shown to be tumorigenic in vivo, with high plasma TNF-α levels associated with poor disease outcome." (PMID 12402142, 2002). "In the Colon 38 tumour, in situ TNF synthesis is probably responsible for sustaining the vascular effect of DMXAA and inducing haemorrhagic necrosis." (PMID 12085190, 2002). "Firstly, apoptosis of endothelial cells was observed in Colon 38 tumour sections within 30 min after administration, well before the time at which TNF is detectable in plasma or tumour tissue." (PMID 12085190, 2002). "In the presented study we performed ILP with the combination of actinomycin D and TNF to study their potential of inducing a tumour response." (PMID 11953868, 2002). "The results support the concept that the late, tumour-specific vascular response in WT mice treated at this dose is TNF-dependent." (PMID 12177785, 2002). "In the univariate analysis patients without nodal metastatic involvement (P = 0.02), less advanced tumour stage (P = 0.02) or TNF-α and TGF-β positive cancers (P = 0.01 and P = 0.03) showed a favourable prognosis in terms of overall survival." (PMID 10945495, 2000). "Several possible mechanisms for the synergistic anti-tumour effects between tumour necrosis factor alpha (TNF-α) and melphalan after isolated limb perfusion (ILP) have been presented." (PMID 10737379, 2000). "The increase in the anti-tumour action by thalidomide in combination with DMXAA corresponded to an increase in intra-tumoural TNF-α production." (PMID 10360649, 1999). "We studied the feasibility of a perfusion with TNF-α and assessed its anti-tumour effects in tumour models differing in tumour vasculature." (PMID 10027309, 1999). "In this report we have investigated the synthesis of TNF-α mRNA in hepatic, splenic and tumour tissue." (PMID 10360649, 1999). "We conclude that the combination of TNF and melphalan has strong synergistic anti-tumour effects in our model, just as in the clinical setting." (PMID 10389992, 1999). "The applicability of TNF-α in isolated kidney perfusion for human tumours seems, therefore, questionable." (PMID 10027309, 1999). "Co-administration of thalidomide with DMXAA increased anti-tumour activity and increased intra-tumoural TNF-α production approximately tenfold over that obtained with DMXAA alone." (PMID 10360649, 1999). "Administration of DMXAA to mice with established transplantable tumours elicits rapid vascular collapse selectively in the tumour, followed by extensive haemorrhagic necrosis mediated primarily through the production of TNF-α." (PMID 10360649, 1999). "There was evidence that tumour necrosis factor alpha (TNF-alpha) was involved in tumour-stimulated monocytic proMMP-9 production." (PMID 9743290, 1998). "The cytokine tumour necrosis factor alpha (TNF-alpha) and the enzyme thymidine phosphorylase (TP) are two factors known to promote tumour angiogenesis." (PMID 9649140, 1998). "The level of TNF-alpha in all liver tissue samples and some of the tumours after treatment by isolated liver perfusion was much higher than the peak serum concentrations obtained after systemic administration of the maximum tolerated dose of TNF-alpha." (PMID 9166943, 1997). "Effects of amphotericin B on production of endogenous tumour necrosis factor alpha (TNF-alpha) and anti-tumour activity in mice was examined." (PMID 9184176, 1997). "Our results demonstrate that TNF-alpha and IL-1 beta stimulate the plasminogen activation system in tumour cell but the responses differed even in cells derived from the same tissue origin." (PMID 8826848, 1996).
tumor (continued). "The in vivo anti-tumour effects of the hybrid TNF-alpha s with a molecular size from 100 to 110 kDa, which had more than 50% of specific bioactivity of native TNF-alpha, were significantly superior to other PEG-TNF-alpha s." (PMID 8855980, 1996). "To design hybrid tumour necrosis factor-alpha (TNF-alpha) applicable to systemic anti-tumour therapeutic use, we assessed the relationships among the molecular size of hybrid TNF-alpha, in vitro bioactivity and in vivo anti-tumour potency." (PMID 8855980, 1996). "This study was conducted to increase the anti-tumour potency and reduce the toxic side-effects of tumour necrosis factor alpha (TNF-alpha)." (PMID 7734321, 1995). "In vitro and in vivo studies have suggested synergistic anti-tumour activity of combined hyperthermia and tumour necrosis factor alpha (TNF-alpha)." (PMID 7779705, 1995). "In view of the large variability in tumour sensitivity for TNF-alpha, the clinical usefulness of this combined treatment modality has to be determined." (PMID 7779705, 1995). "The aim of this study was to investigate mechanisms of anti-tumour activity and necrosis induced by combinations of tumour necrosis factor alpha (TNF-alpha) and interferon gamma (IFN-gamma)." (PMID 7577463, 1995). "Treatment with TNF-alpha and IFN-gamma caused focal engorgement of tumour capillaries with erythrocytes, intravascular recruitment of polymorphonuclear cells and platelet adherence to the tumour vascular endothelium 4 h after the combined treatment." (PMID 7577463, 1995). "TNF-alpha was expressed focally in 50% of the tumours studied, being largely localised to macrophage-like cells in the stroma." (PMID 7519867, 1994). "The binding and biological activity of human TNF alpha on endothelial and tumour cells has been studied in the presence of monoclonal antibodies (MAbs)." (PMID 1377483, 1992). "Recombinant human TNF (rhTNF) also promoted tumour implantation in all three xenograft models, but its antitumour effects differed from rhIL-1 beta." (PMID 1586593, 1992). "Analysis of peritoneal fluid and tumour xenografts showed that TNF induced murine IL-1 in the tumour bearing mice." (PMID 1586593, 1992). "The ability of MAb 32 to inhibit selectively the actions of TNF alpha on endothelial cells but not on tumour cells suggests a mechanism for enhancement of the anti-tumour action of TNF alpha in vivo when in complex with this antibody." (PMID 1377483, 1992). "Effects of recombinant tumour necrosis factor (TNF) on functional and structural vascular volumes in solid murine Meth A tumours were investigated by injection of Hoechst 33342 and staining for the vascular basement membrane component laminin, respectively." (PMID 2245163, 1990). "With OK-432, however, there was a greater concentration of TNF in the serum than in the tumour homogenates." (PMID 2206945, 1990). "Intravenous injection of BPV into mice bearing the MM46 carcinoma resulted in a greater concentration of TNF in the tumour homogenate than in the serum." (PMID 2206945, 1990). "Two hours after such administration tumour tissues tested were resected from the mice, homogenised, and the TNF activities in the homogenate were assayed using a L-929 fibroblast assay." (PMID 2206945, 1990). "Both TNF-alpha and extracts from the MAC16 tumour caused an enhanced release of amino acids from mouse diaphragm, which was suppressible with indomethacin and heat labile." (PMID 3390373, 1988). "While treatment with AZD4573 led to modest prolongation of survival in an ibrutinib-resistant MCL PDX mouse model, accompanied by downregulation of TNF/NF-B and mTORC1 signaling pathways in murine splenocytes, OxPhos was upregulated suggesting tumor metabolic reprogramming." (PMID 42048618, 2026). "Notably, TNF-α producing activated dendritic cells (CD80+) correlated with enhanced tumor suppression." (PMID 41522339, 2026).
tumor (continued). "The anti-tumor effect of IL-37 results from the suppression of tumor-promoting cytokines, such as IL-1β, which activates IL-6 and TNF, direct effects on tumor cells, and reduction of cell proliferation by interfering with NF-κB, MAPK, and signal transducer and activator of transcription 3 (STAT3)." (PMID 41596472, 2026). "Here, it dissects the molecular mechanisms underlying NK cell dysfunction in cutaneous malignancies and identifies a paradoxical cytokine shift in tumor‐associated NK cells–reduced production of IFN‐γ and TNF‐α alongside elevated amphiregulin (AREG), an EGFR ligand linked to tumor progression." (PMID 41082397, 2026). "Importantly, P. aeruginosa–induced pyroptosis was accompanied by a marked increase in inflammatory cytokines, including IL-6 and TNF-α, and a significant upregulation of PD-L1 expression on tumor cells." (PMID 41484455, 2026). "Furthermore, Ptpn13 knockdown in tumor cells significantly enhanced the expression of the effector cytokines IFNγ and TNFα in CD8+ T cells isolated from CT26-shApc tumors in WT Balbc mice, indicating an increase in CD8+ T cell effector function." (PMID 41486293, 2026). "Additionally, high A3C expression correlated with increased CD8+ T cell infiltration—CD8+ T cells are key mediators of anti-tumor immunity, capable of inducing tumor cell programmed death by releasing perforin, tumor necrosis factor, and interferon." (PMID 41514678, 2026). "Regarding the production of TNF by MCs, both TNF stored in the granules and that produced through protein synthesis stimulate the production of other cytokines, such as IL-1 and IL-6, inducing apoptosis and counteracting tumor growth." (PMID 41596472, 2026). "The Gal-9/TIM-3 pathway partially activates cytokine production IL-6, IL-8, and IL-10, but not IL-1β, IL-12p70, or TNFα in response to LPS in gastric cancer tissue-derived tumor-associated macrophages, TAMs." (PMID 41596489, 2026). "Instead of producing IFN‐γ and TNF‐α, they elevate amphiregulin, a tumor‐promoting factor." (PMID 41082397, 2026). "Examination of TNF-α expression therefore provides a mechanistic bridge between the upstream receptor-kinase signalling events documented above and the functional cellular responses that determine tumour cell fate." (PMID 41596561, 2026). "Within the tumor microenvironment, effective tumor control was strongly associated with higher frequencies of TNF-α-producing dendritic cells, IFN-γ-producing NK cells, and CD8+ T cells secreting both IFN-γ and TNF-α." (PMID 41522339, 2026). "This review aims to provide insight and background on molecular switches, cellular context, and TNF receptor dynamics that determine the role of TNF-α as both tumor suppressor and promoter in different models, which is essential for deriving maximal benefit from TNF therapies." (PMID 41651411, 2026). "Furthermore, activating NK cells has shown that treating pro‐tumour neutrophils with IFN‐γ and TNF‐α can alter their role from tumour promotion to tumour suppression." (PMID 41503514, 2026). "A recent review suggested recruitment of ASCs from ppWAT into PCa cells and the TME are precursors to tumor stromal cells and cancer‐associated fibroblasts and a source of IL‐6, TNFα, CXCL1, CXCL5, CXCL8, CXCL12, MCP‐1, and leptin facilitating tumor angiogenesis and cancer cell proliferation." (PMID 41450167, 2026). "It is hypothesized that HMGCR and TNF-α jointly drive a tumor-growth-promoting microenvironment rich in cholesterol and inflammatory signals." (PMID 41450917, 2025). "CD4+ T helper cells have a dual role: Th1 cells support antitumor responses and can directly kill tumor cells through cytokine release (IFN-γ and TNF-α), while Th2 cells promote tumor progression by secreting anti-inflammatory mediators, such as IL-4 and IL-13, that suppress immune activity." (PMID 41230456, 2025).
tumor (continued). "Elevated levels of specific pro-inflammatory cytokines, such as IL-1, IL-6, IL-8, and TNF-α contribute to tumor progression and invasion by promoting cell proliferation, epithelial–mesenchymal transition (EMT), and vascularization, while also enhancing the tumor’s ability to evade immune detection." (PMID 41007256, 2025). "In addition, probiotics can upregulate IFN-γ and TNF-α in NK cells to mediate the differentiation of oral squamous cancer stem cells, subsequently suppressing tumor development while attenuating proinflammatory cytokine cascades." (PMID 40770084, 2025). "For example, whether TNF-α secreted by M1-like macrophages in the tumour microenvironment can promote angiogenesis depends on the amount of TNF-α secreted and whether pericytes are present." (PMID 39847394, 2025). "Tumor cells can then rapidly proliferate following the relief of the TNFα-mediated suppression." (PMID 40301543, 2025). "Both IFNγ and TNFα are important inflammatory mediators in the tumor microenvironment." (PMID 39896512, 2025). "TNF-α is chronically produced at low levels within the tumour microenvironment." (PMID 39941741, 2025). "During tumor progression, often accompanied by CC, this balance is disrupted, driven by the secretion of various pro-inflammatory catabolic factors by immune and cancer cells, such as tumor necrosis factor-α (TNFα)." (PMID 40283883, 2025). "We hypothesized that the loss of T cell-induced phosphorylation of TNF signaling proteins in sensitized tumor cells might stem from changes in the assembly of the TNFR1 signaling complex upon TNF stimulation." (PMID 41315176, 2025). "The upregulation of BAX and TNF expression in macrophages induces infiltration of aberrantly activated macrophages, which display dysfunctional differentiation in tumor tissues, altered immune responses, and activation of the tumor necrosis factor (TNF) pathway in UCEC macrophages." (PMID 39744500, 2025). "Results of the in vivo study included suppression of EAC tumor burden, enhanced apoptosis (Annexin V/PI), reduced IL-6 and TNF-α cytokines, and preserved liver/kidney function, confirming synergistic antitumor and immunomodulatory effects with a favorable biosafety profile." (PMID 40943339, 2025). "Furthermore, APOL1, TNF, and VIM are co-expressed in myeloid cells, while APOL1 and TNF are also co-expressed in T cells and NK cells, indicating the association between APOL1 and the lactylation–PANoptosis axis in regulating tumor progression." (PMID 40649778, 2025). "Moreover, ABO blood group status is associated with circulating inflammatory markers suchas intercellular adhesion molecule-1 (ICAM-1) and tumor necrosis factor-alpha (TNF-α), which are involved in the tumor microenvironment." (PMID 41466714, 2025). "TNF - α also promotes the recruitment of immune cells to the tumor site." (PMID 39980561, 2025). "Moreover, in murine models, SC has been reported to activate immune effector cells, particularly macrophages, enhancing the production of pro-inflammatory cytokines such as TNF-α, which contribute to tumor cell apoptosis and immune surveillance." (PMID 41471781, 2025). "The increased conjugate formation between NK cells and BC cells following combined treatment with IFN-γ + TNF-α was correlated with enhanced interaction between NK cells and tumor cells and an increased apoptotic state of the latter, resulting in reduced spheroid size." (PMID 41102150, 2025). "NF-κB activation triggers inflammatory pathways, establishing a positive feedback loop with a rise in chemokine expression (e.g., CXCL8 and CCL2), nitric oxide synthase (NOS), COX-2, and inflammatory mediators (IL-6, IL-8, and TNF-α), thereby fostering tumor development." (PMID 40420174, 2025).
tumor (continued). "Copper promotes angiogenesis by activating several pro-angiogenic factors, namely vascular endothelial growth factor (VEGF), fibroblast growth factor 2 (FGF2), tumor necrosis factor (TNF), and interleukin-1 (IL-1), thereby promoting tumor initiation, growth, and metastasis." (PMID 40164592, 2025). "Chronic inflammation caused by excessive TNF-α leads to a tumor-supportive rather than a tumor-suppressive environment." (PMID 40309351, 2025). "Notably, many studies report a shift toward an M2-like phenotype, characterized by an increased expression of IL-10 and VEGF, along with decreased TNF-α levels—features indicative of immunosuppressive reprogramming and a tumor-permissive immune profile." (PMID 40940834, 2025). "Based on the IPA of differentially expressed genes, we discovered activity changes of several pathways significantly associated with tumor behavior were activated over the course of surgery (FDR <5%), including IL-6, IL-8, HMGB1, HIF1α, IL-1, TGFβ, and TNFα signaling." (PMID 40331601, 2025). "They found that interleukin-1β (IL-1β) and tumor necrosis factor-α (TNF-α) were primarily secreted by dendritic cells (DCs), and macrophages with a marked elevation in these cytokines in tumors colonized by ΔppGpp all through the phase of tumor suppression." (PMID 40519767, 2025). "Notably, this increase was substantially reduced when IL-1 or TNF-α receptors were genetically ablated, underscoring the essential roles of TNF-α and IL-1 in Upp1 upregulation in tumor cells cocultured with macrophages." (PMID 41243973, 2025). "In the tumor immune microenvironment, CD4+ T cells can stimulate and maintain the differentiation of macrophages, CD8+ T cells and NK cells by secreting cytokines such as IFN-γ, TNF and IL-2, and inhibit angiogenesis of tumor, thus playing an anti-tumor effect." (PMID 40176817, 2025). "Importantly, TNF-α contributes to angiogenesis (see Section 4), further supporting tumor dissemination." (PMID 40868199, 2025). "Moreover, SC has shown immunomodulatory properties, notably stimulating macrophages and enhancing the production of TNF-α, a cytokine involved in tumor cell apoptosis and immune surveillance." (PMID 40806596, 2025). "Collectively, purified recombinant IFNγ and TNFα could fully recapitulate the effects of tumor-bearing serum." (PMID 41322654, 2025). "In the context of HL, where the tumor microenvironment is highly inflammatory, the presence of omega-3 may limit the activity of cytokines such as IL-6, TNF-α or IL-1β, which promote the proliferation of Reed–Sternberg cells and the progression of the disease." (PMID 41374067, 2025). "However, a recent report showed that tumor-associated myeloid cells secreted TNF-α upon STING activation and induced apoptosis of tumor endothelium to promote tumor immunity." (PMID 39817453, 2025). "This study investigated the effects of the cytokines IFN-γ and TNF-α, used at low, non-toxic doses, on the susceptibility of 2D BC cell cultures and 3D BC spheroids to NK cell-mediated anti-tumor activity." (PMID 41102150, 2025). "P.g. induces macrophage polarization into tumor-associated M2, upregulating gene expression of pro-tumoral molecules (suprabasin, IL-1R2, IL-18, and TGF-α) while suppressing multiple anti-tumor cytokines (TNF-β, IFN-β, TRAIL, and TNF-α) in Cal-27 cells." (PMID 40924302, 2025). "In addition, other studies suggest that cytotoxic T cells’ production of proinflammatory cytokines such as IFN‐γ and TNF‐α can trigger upregulation of genes that mediate apoptosis resistance and increase tumor cell proliferation and invasion in GBM cells." (PMID 40498413, 2025). "Notably, R. gnavus supplementation potentiates anti-PD-1-mediated tumor elimination in mice by inducing a proinflammatory intestinal microenvironment, which enhances the proliferation and infiltration of TNF-producing CD4+ T cells into tumors." (PMID 40770084, 2025). "CTLs also release IFN-γ and TNF-α, which inhibit tumor proliferation." (PMID 40565031, 2025).